TAF9 (TATA-box binding protein associated factor 9)
Description:
The TFIID basal transcription factor complex plays a major role in the initiation of RNA polymerase II (Pol II)-dependent transcription. TFIID recognizes and binds promoters with or without a TATA box via its subunit TBP, a TATA-box-binding protein, and promotes assembly of the pre-initiation complex (PIC). The TFIID complex consists of TBP and TBP-associated factors (TAFs), including TAF1, TAF2, TAF3, TAF4, TAF5, TAF6, TAF7, TAF8, TAF9, TAF10, TAF11, TAF12 and TAF13. TAF9 is also a component of the TBP-free TAFII complex (TFTC), the PCAF histone acetylase complex and the STAGA transcription coactivator-HAT complex. TAF9 and its paralog TAF9B are involved in transcriptional activation as well as repression of distinct but overlapping sets of genes. Essential for cell viability. May have a role in gene regulation associated with apoptosis.
Synonyms: TAFII-31; TAFII31; TAFII-32; TAFII32; TAF2G; TAFIID32; MGC5067; CGI-137; MGC1603; MGC3647; AD-004; MGC:5067; STAF31/32
Tractability: Small molecule: a structure with a bound ligand is known. PROTAC: ubiquitination databases record sites on it; its protein half-life has been measured.
Gene: Protein-coding gene on chromosome 5 (69,362,026 to 69,370,026, reverse strand). Ensembl gene ENSG00000273841.
Subcellular location: Nucleus
Subcellular location (Human Protein Atlas): Nucleoplasm
Pathways (Reactome):
Gene expression (Transcription): RNA Polymerase II Pre-transcription Events; RNA Polymerase II Promoter Escape; RNA Polymerase II Transcription Initiation; RNA Polymerase II Transcription Initiation And Promoter Clearance; RNA Polymerase II Transcription Pre-Initiation And Promoter Opening; RNA polymerase II transcribes snRNA genes
Disease: HIV Transcription Initiation; RNA Polymerase II HIV Promoter Escape; Transcription of the HIV genome
Chromatin organization: HATs acetylate histones
Gene Ontology:
Molecular function: ATPase binding; C2H2 zinc finger domain binding; DNA binding; DNA-binding transcription factor binding; histone acetyltransferase activity; protein binding; transcription cis-regulatory region binding; transcription coactivator activity; RNA polymerase II general transcription initiation factor activity; protein heterodimerization activity
Biological process: box C/D snoRNP assembly; mRNA transcription by RNA polymerase II; negative regulation of apoptotic process; negative regulation of proteasomal ubiquitin-dependent protein catabolic process; positive regulation of response to cytokine stimulus; positive regulation of transcription by RNA polymerase II; positive regulation of transcription initiation by RNA polymerase II; protein stabilization; regulation of transcription by RNA polymerase II; response to interleukin-1; RNA polymerase II preinitiation complex assembly; DNA damage response; positive regulation of DNA-templated transcription; regulation of DNA repair; regulation of DNA-templated transcription; regulation of RNA splicing; chromatin remodeling; DNA-templated transcription initiation
Cellular component: MLL1 complex; nucleoplasm; nucleus; pre-snoRNP complex; SAGA complex; transcription factor TFIID complex; transcription factor TFTC complex
Genetic constraint (gnomAD): Loss-of-function variants: 10 observed, 16.96 expected, observed/expected ratio (o/e) 0.59, 90% interval 0.36 to 1. The upper end of that interval is the gene's LOEUF score, 1, which puts it in group 4 of 6, group 1 being the genes least tolerant of losing a copy. Missense variants: 288 observed, 333.05 expected, observed/expected ratio (o/e) 0.86, 90% interval 0.79 to 0.95. Synonymous variants: 105 observed, 125.53 expected, observed/expected ratio (o/e) 0.84, 90% interval 0.71 to 0.98.
Homologues: Orthologues: dog TAF9 (98% identical), pig TAF9 (97% identical), mouse Ak6 (95% identical), mouse Taf9 (95% identical), rat Taf9 (95% identical), guinea pig TAF9 (95% identical), chimpanzee TAF9 (93% identical), tropical clawed frog taf9b (80% identical), zebrafish taf9 (77% identical), Drosophila melanogaster Taf9 (37% identical), Caenorhabditis elegans taf-9 (22% identical). Paralogues in human: TAF9B (78% identical).
Diseases named in the same sentence as TAF9 in open-access papers:
TAF9 is named in the same sentence as 23 diseases in open-access papers, as found by Europe PMC text mining. Sharing a sentence is not in itself a finding about the gene and the disease. The quoted sentences say what the papers report.
gout (2 papers, 2020 to 2021). A condition characterized by painful swelling of the joints, which is caused by deposition of urate crystals. "The positive association between anti-TAF9 and anti-HCMVpp65422-439 antibody activities was significant in SLE, SS, gout, and RA; however, most sera from SS, gout, or RA patients had a poor response to HCMVpp65422-439 or TAF9 in the ELISA test." (PMID 32541894, 2020). "In addition, the IgG antibody responses to CMVpp65 and the human TAF9 protein were evaluated using the sera from rheumatic patients with CMV IgG-positive statuses, including SLE (n = 163), SS (n = 64), RA (n = 76), gout (n = 70), and AS (n = 52)." (PMID 34442018, 2021).
lupus (2 papers, 2020 to 2021). "Whether the elevation of anti-TAF9 IgG is associated with anti-CMV reactivity in human lupus remains unclear." (PMID 34442018, 2021).
Non-alcoholic Fatty Liver Disease (2 papers, 2021 to 2025). "Additionally, another study indicated that Danshensu protects against nonalcoholic fatty liver disease by significantly enhanced fatty acid β-oxidation and decreased lipid droplet accumulation in the histone deacetylase 1/TATA-box binding protein associated factor 9-dependent pathway." (PMID 40225863, 2025).
Sjögren syndrome (2 papers, 2020 to 2021). "In the current study, we enrolled patients with Sjögren’s syndrome to determine the correlation between anti-HCMVpp65422-439 and anti-TAF9 antibodies." (PMID 32541894, 2020).
esophageal (1 paper, 2022). "The TAF9(TATA-binding protein) was also identified as a prognostic gene in a DNA-repair-related gene model for esophageal cance, our results showed that MHPS was also associated DDR, which suggested that TAF9 might involved in tumor processes, and discovered as a potential target in TNBC." (PMID 36105819, 2022).
hepatic carcinoma (1 paper, 2022). "The “five-gene” score (TAF9, RAMP3, HN1, KRT19, and RAN) was built to evaluate the genetic role in hepatic carcinoma and reported strong prognostic relevance." (PMID 35200757, 2022).
ischemia (1 paper, 2022). A hypoperfusion of the BLOOD through an organ or tissue caused by a PATHOLOGIC CONSTRICTION or obstruction of its BLOOD VESSELS, or an absence of BLOOD CIRCULATION. "Therefore, we have demonstrated that TAF9 plays a key role in RGC protection after ON ischemia." (PMID 35955492, 2022).
ovarian carcinoma (1 paper, 2014). A malignant neoplasm originating from the surface ovarian epithelium.
rheumatic diseases (1 paper, 2021). "In the present study, we examined the seroprevalence of anti-CMV IgG/IgM, anti-CMVpp65 IgG, and anti-TAF9 IgG among patients with five common rheumatic diseases." (PMID 34442018, 2021). "Compared to those from individuals with other rheumatic diseases, sera from SLE patients showed the highest seropositivity for antibodies against CMVpp65 and/or TAF9." (PMID 34442018, 2021).
viral infection (1 paper, 2020). "The cross-reactivity between serum anti-HCMVpp65422-439 and anti-TAF9 antibodies in SLE sera implied the possibility that the occurrence of the epitope is spreading between HCMVpp65 and TAF9 proteins during viral infection." (PMID 32541894, 2020).
tumor (7 papers, 2004 to 2024). "Although alterations of several genes (such as Hebp1, Eno1, and Taf9) other than Ankrd52 are more frequently detected in our tumor profiling, their targeting sgRNAs exhibited much less enrichment or fold-change as compared to those of Ankrd52." (PMID 34853298, 2021). "The immunohistochemistry (IHC) results demonstrated that DYNC1H1, GTPBP4, PRKDC, RBM19, SF3B4, SPATS2 and TAF9 were significantly increased in HCC tumor cells compared to normal hepatocytes." (PMID 33411682, 2020). "While TAF4B could potentially be involved in mediating anti-apoptotic effects, TAF9 is illustrative of a TAF acting as a putative tumor suppressor, since it is downregulated or deleted in 98% of HGSC." (PMID 24653979, 2014). "An evaluation of molecular signatures based on tumor expression of 20 metastasis-associated microRNAs, a comparison of microRNA expression between tumor and adjacent benign tissue, or the tumor expression of five genes (HN1, RAN, RAMP3, KRT19 and TAF9) can also predict prognosis." (PMID 28943622, 2015). "In pooled differential expression analyses between healthy and tumor samples more proteins were downregulated, while several proliferation-related proteins (e.g., POL2RK, MEN1, MNAT1, TAF9, or SDHC) and biological processes were upregulated." (PMID 38802361, 2024). "Considering the tumor heterogeneity of the two clusters, we identified six prognostic genes (PIM2, PET117, SMARCA5, TAF9, ABCB10, MKP1) among the m6A-hypoxia genes and developed a scoring system to evaluate m6A modification patterns and hypoxia status." (PMID 36105819, 2022).
cancer (3 papers, 2014 to 2022). A tumor composed of atypical neoplastic, often pleomorphic cells that invade other tissues. "The interruption of interactions between Hedgehog transcription factors (Gli proteins) and TAF9 reduces Gli/TAF9-dependent transcription, suppresses cancer cell proliferation, and reduces xenograft growth." (PMID 35955492, 2022). "For instance, genes such as SAC3D1, NELFCD, and TAF9 (TATA-box binding protein associated factor 9) were implicated in the DNA repair pathway and are associated with survival in some cancers." (PMID 33477315, 2021).
TAF9 also shares sentences with these, for which no sentence is quoted: ankylosing spondylitis (1 paper); Autoimmunity (1); breast carcinoma (1); colon cancer (1); Diamond-Blackfan anemia (1); glomerulonephritis (1); infection (1); infertile (1); neuroblastoma (1); neuroendocrine tumor (1); rheumatoid arthritis (1).